LEP (leptin)
Diseases named in the same sentence as LEP in open-access papers (continued):
Sharing a sentence is not in itself a finding about the gene and the disease.
Obesity (continued). "Moreover, it is important to highlight that altered leptin transport across the BBB, due to hypertriglyceridemia, paired with peripheral leptin resistance and central leptin resistance, could play a crucial role in the development and progression of obesity." (PMID 33946540, 2021). "However, during obesity, leptin is not effective at reducing appetite and body weight." (PMID 34064024, 2021). "Thus, no response may result in, for example, obesity, while an exaggerated signal may indicate leptin resistance." (PMID 34684668, 2021). "Although the animals in our study did not have obesity, hyperleptinaemia, or systemic leptin resistance, we believe that the main mechanism of the cardioprotective effect of a reduced blood leptin level is increased sensitivity of the myocardium and vascular endothelium to leptin." (PMID 34903800, 2021). "Another pathway is the association between overweight and higher fat-derived hormone (e.g., levels of leptin in LPCD patients have been reported to be higher with the severity of the disease,), which might explain the higher prevalence of overweight and obesity in LCPD patients." (PMID 33407313, 2021). "However, unlike leptin, adiponectin is elevated in lean adipose tissue and decreases with obesity." (PMID 33859943, 2021). "We conclude that leptin is a pyrexic hormone (increases the regulated body temperature) but that it is not thermogenic, at least not in the standard mouse models used, and that the obesity in the ob/ob mice thus evolves without reinforcement from decreased thermogenesis." (PMID 31774114, 2020). "Future studies need to measure leptin in conjunction with the other appetite-regulating peptides (acylated ghrelin, PYY, GLP-1, CCK and PP) to enable a better understanding of how exercise-induced responses to appetite-regulating hormones might differ in obesity." (PMID 32729763, 2020). "During leptin resistance, there is an increased secretion of leptin from white adipose tissue, but this leptin does not bind with its receptor (LEP-R) present on hypothalamus in brain, causing resistance to the leptin and increasing the body weight which leads to the obesity." (PMID 31929574, 2020). "However, the precise role of leptin on obesity-induced cardiomyopathy is not completely understood." (PMID 32346034, 2020). "This hypothesis is supported by the observations that intratumoral leptin delivery provides no benefit in obese mice, in contrast to controls, and that neutralization of leptin improves immunotherapy responsiveness in mice with diet-induced obesity." (PMID 33170123, 2020). "Although a single injection of leptin does not imitate the leptin levels that are characteristic of obesity, this model allows us to assess whether the foetuses on day 12 of development are sensitive to the action of maternal leptin and to reveal an acute response from the foetuses and placentas." (PMID 31703240, 2020). "With a significant positively correlation with serum hsCRP levels, AHR transcripts in PBMCs may represent as a novel mediator of the immune disturbance and meta-inflammation in obesity and T2D patients, independent of leptin, the previously-known key metabolic controller and immune modulator." (PMID 32849564, 2020). "The mechanisms by which obesity predisposes children to IIH have not been fully elucidated, however, the link between obesity and this condition is most likely to be in the different substances, from pro-inflammatory cytokines to leptin, secreted by the adipose tissue." (PMID 32947869, 2020). "Although it has not been described, we hypothesize that as occurs with leptin, this adipokine may be increasingly secreted during the development of obesity, and probably part of this secretion occurs through EVs as validated by immunoblot in the present research." (PMID 32214011, 2020).
Obesity (continued). "Furthermore, this hormone reduced CLS formation which is characteristic of obesity, showing that in addition to its metabolic effects, melatonin acts to reduce inflammation, that was confirmed by the lower expression of pro-inflammatory cytokines in WAT, such as leptin and Mcp-1." (PMID 31749764, 2019). "Thus, the aim of this study was to test the hypothesis that unsaturated high-fat diet-induced obesity does not generate endothelial dysfunction via increasing the vascular leptin/Akt/eNOS signaling." (PMID 30949067, 2019). "These mutations may cause nonsense-mediated mRNA decay, defective secretion or the phenomenon of biologically inactive leptin, but typically lead to an absence of circulating leptin, resulting in a rare type of monogenic extreme obesity with intense hyperphagia, and serious metabolic abnormalities." (PMID 31067764, 2019). "Therefore, this double behavior of leptin and the modulation of vascular tone may help explain why obesity is not always accompanied by high blood pressure." (PMID 30949067, 2019). "Although visfatin serum levels were comparable between patients with or without type 2 diabetes or obesity, the authors observed a significant correlation between visfatin levels and biomarkers of liver and kidney dysfunction and other adipokines such as resistin and leptin." (PMID 31569348, 2019). "Hence, leptin action is crucial for the maintenance of a correct lipid metabolism in hepatic cells, and we suggest the use of RSV as a natural agent in the formulation of functional foods to restore leptin signalling and subsequently combat the onset of obesity." (PMID 31842467, 2019). "Positive effects of leptin replacement on minute ventilation and tidal volumes during flow-limited breathing in ob/ob mice were also previously demonstrated by several studies, indicating that leptin treatment may have a potential to treat both OSA and obesity hypoventilation." (PMID 29675134, 2018). "Intriguingly, in this study, celastrol blocks obesity progression in mice without reducing food intake or affecting hypothalamus metabolic genes expression, possibly because these mice didn’t develop severe leptin resistance as the DIO model used in Liu’s paper." (PMID 30042690, 2018). "Finally, to determine which blood RSV metabolites could potentially be involved in the anti-obesity effects of RSV, we used the Spearman’s correlation test to evaluate the relationship of RSV metabolites with body and fat mass as well as with leptin sensitivity in each peripheral tissue." (PMID 30441779, 2018). "Thus, the hypothesis that the action of TTI and pTTI are related to satiety in obesity is likely dependent on the action of these inhibitors on leptin and not on CCK, as seen for eutrophic animals." (PMID 29322840, 2018). "However, the leptin level has not been analyzed in this diet-induced-obesity (DIO) minipig model." (PMID 30551684, 2018). "However, mice lacking PrRP in LEPRs producing neurons (PrRP-Cre, and Leprflox/flox mice) only develop mild obesity mainly due to lower energy expenditure, which suggests that PrRP-producing neurons do not represent a major relay between leptin and the melanocortin signaling pathway." (PMID 28690493, 2017). "However, serum leptin is usually elevated in obese individuals, which suggests that there might be a state of leptin resistance, whereby leptin is not able to control obesity by appropriately reducing food consumption." (PMID 28400989, 2017). "In addition to phosphorylation, leptin-induced STAT3 methylation by protein arginine N-methyltransferase 2 (PRMT2) was also shown to occur, and PRMT2−/− mice are lean, hypophagic, have reduced serum leptin levels and are more resistant to diet-induced obesity (DIO) compared to wild-type littermates." (PMID 28270795, 2017).
Obesity (continued). "Notably, this increase in pain-related behaviors occurred in both Long-Evans and Sprague-Dawley rats despite the fact that the 6-week HFD exposure induced obesity (e.g., increased insulin, leptin, weight, and percent body fat) in the Long-Evans, but not Sprague-Dawley, strains." (PMID 28871134, 2017). "The leptin-to-adiponectin ratio might, therefore, reflect the endocrine function of adipose tissue and provide a potentially useful measure of insulin resistance in subjects with obesity, metabolic syndrome, diabetes mellitus or non-diabetic mellitus." (PMID 28448547, 2017). "The lack of the leptin gene leads to a lethal form of obesity development and an alteration in leptin pathway homeostasis, and the abnormally high leptin level observed in obese subjects could result in leptin resistance because of decreased leptin receptor signaling." (PMID 27983705, 2016). "However, since circulating levels of leptin are elevated with obesity, and most obese patients are in a state of leptin resistance, leptin therapy may not be beneficial for most obese patients." (PMID 27375555, 2016). "Therefore, in the obesity-related cancer environment where many cytokines show altered profiles, angiogenesis factors (i.e., EGF, VEGF, and PAI-1) and inflammatory mediators (i.e., IL-1, IL-6, TNF-α, and leptin) are thought to cultivate a favorable environment for neoplastic cell growth." (PMID 26794215, 2016). "Therefore it may be hypothesized that periodontal inflammation may have a greater influence on GCF cytokine levels (including leptin) rather than the increased systemic inflammatory burden due to obesity." (PMID 27795608, 2016). "However, leptin is not a suitable treatment for most patients with obesity as they already have high circulating levels of leptin because they have developed leptin resistance, a condition where leptin is unable to induce its effect of lowering of food intake and therefore body weight." (PMID 25954145, 2015). "Intriguingly, the leptin/NtsR-1 system may have more impact in regulating non-homeostatic feeding: while mice lacking NtsR1 exhibit normal chow intake, they over consume palatable, high-fat diet or a sucrose solution that promotes obesity." (PMID 25741247, 2015). "Leptin levels may be used to predict the development of MS independent of obesity." (PMID 24944619, 2014). "Similar to leptin, oleoyl-estrone levels correlate with adiposity in humans, but obese individuals have lower circulating OE levels than would be expected by this model, perhaps suggesting that resistance to this hormone does not develop in the context of obesity." (PMID 26237477, 2014). "The fact that OW/O Tepehuán present relatively low leptin levels suggests that obesity is not under by the same biochemical parameters in both populations could be related to differences in the nutritional qualities of the diet, which could affect fatness degree and therefore leptin levels." (PMID 24825928, 2014). "However, studies with larger size samples reported a negative correlation between plasma leptin levels and major depression, hence supporting the idea that decreased leptin signaling may be a shared biological alteration in both obesity and depression." (PMID 25386150, 2014). "Therefore, for Taiwanese or Asian, leptin may not be the best predictor for metabolic syndrome, only for general obesity alone." (PMID 24684833, 2014). "Previous studies supporting the hypothesis that obesity alters isoprenoid signaling include work demonstrating that mice lacking the obesity gene product leptin (ob/ob) exhibit increased expression of the isoprenoid synthesis enzyme geranylgeranyl diphosphate synthase (GGPS) compared to controls." (PMID 23840226, 2013).
Obesity (continued). "Together, the altered hormonal and inflammatory milieu of obesity may contribute significantly to cancer growth and progression via promoting mitogenesis (e.g., leptin, IGF-1, insulin), angiogenesis (e.g., VEGF, IL6, IL8), and invasion (e.g., leptin, IL6, PAI-1, CCL5, CCL2)." (PMID 23573093, 2013). "Thus, the degree of obesity as well as the presence or absence of TNFα may be of importance in determining the protective effects of leptin." (PMID 23125848, 2012). "When we treated overnight-deprived Nbea+/− mice with leptin at the time of chow refeeding, they ate significantly less food than control animals receiving only saline injection, indicating that leptin resistance is unlikely to explain the obesity of Nbea+/− mice." (PMID 22438821, 2012). "Thus, whether high blood pressure without obesity stimulates leptin synthesis in adipocytes and/or other types of cells is not known." (PMID 23270329, 2012). "Therefore, n-3 PUFAs may be involved in leptin resistance in obesity, although no consistent conclusion has been reached on the relationships between them." (PMID 21609458, 2011). "Our finding that both systemic and cerebroventricular administration of leptin produced early increases in activity in obob mice before substantial decreases in body weight provides evidence for a direct effect of leptin at least partially independent of reversal of obesity." (PMID 21853117, 2011). "Treatment of obob mice for three weeks with pharmacologic doses of leptin increases locomotor activity and substantially decreases adiposity, but this late effect of leptin on activity could be secondary to reversal of the obesity as opposed to a direct effect of leptin on this behavior." (PMID 21853117, 2011). "Moreover, leptin induces VEGF/VEGFR-2 expression, angiogenesis and growth of human ovary cancer xenografts in nude mice and in 7,12- dimethylbenz[a]anthracene (DMBA)-diet-induced-obesity (DIO) mouse models of breast cancer (Gonzalez-Perez, Manuscript in preparation)." (PMID 21731759, 2011). "We have shown that the obesity that follows cachexia after the treatment of hypothalamic tumors in children younger than one year old is not due to dysregulation of leptin secretion, and that the leptin concentrations and sOB-R remain regulated by factors like testosterone." (PMID 19341477, 2009). "Also, some authors could not find correlation between the OSA severity and the leptin values when corrected for obesity but others did." (PMID 18828917, 2008). "Serum leptin levels were significantly higher in individuals with T2DM and obesity compared to those without obesity (P < .05)." (PMID 41239622, 2025). "HDL-C showed positive correlations with QUICKI, BUN, and serum adiponectin, while negative correlations with the number of MetS criteria, obesity parameters (BMI, %fat, and fat mass), IR parameters (plasma insulin and HOMA-IR), plasma TG, and serum leptin." (PMID 41162612, 2025). "This study aims to investigate the relationship between serum leptin, lipid metabolism, HbA1c, and renal function in individuals with T2DM and obesity and individuals with T2DM without obesity." (PMID 41239622, 2025). "SIM1 haploinsufficiency (SIM1+/−) leads to obesity, marked by hyperphagia without reduced energy expenditure, underscoring SIM1’s role in energy homeostasis and the leptin–melanocortin–oxytocin pathway." (PMID 40428410, 2025). "Dysregulation through compromised BDNF signaling within the hypothalamic neural circuits, due to a lack of leptin‐induced BDNF mRNA translation can lead to leptin resistance, resulting in obesity." (PMID 39853792, 2025). "In line with obesity and increased fat deposition, HFHSD but not RevD mice showed increased fed leptin in plasma (ANOVA: gender P = 0.820, diet P < 0.001, interaction P = 0.800)." (PMID 39302596, 2024).
Obesity (continued). "In support of this concept, well-established mouse models of obesity, including high-fat diet (HFD)-fed WT mice and mice lacking the satiety hormone, leptin, demonstrate marked reduction in hepatic TDAG51 protein levels." (PMID 38237682, 2024). "Thus leptin might not be an ideal obesity indicator in this study." (PMID 38317220, 2024). "The cell-signaling proteins, such as leptin, adiponectin, and progranulin (PGRN) are secreted from adipose tissues and act like cytokines in the obesity-related impact on non-adipose tissues." (PMID 38532900, 2024). "In this negative feedback loop, leptin plays a predominant role, as leptin inhibits adipocyte TET2 significantly in the context of obesity." (PMID 38561362, 2024). "Conversely, in late obesity, after the establishment of leptin resistance at 16 wk of HFD feeding, the disruption of canonical and noncanonical leptin signalling leads to failure in NLRP3 inflammasome activation and M1 macrophage regulation." (PMID 38580672, 2024). "The interaction analysis showed that combination of both asthma and obesity had significant effects on IL-5, IL-10, IL-17A, IL-33, TNF-α, and leptin, but the effects were not synergistic or additive." (PMID 39902293, 2024). "Although these findings generally support the role of leptin as a promising MSC priming agent, they do not necessarily indicate a beneficial effect of leptin on MSC viability and function in pathological contexts, including obesity." (PMID 36750692, 2023). "Consequently, early identification of individuals with DCV and rare VUS in leptin-melanocortin signalling pathway genes allows for a more accurate diagnosis of the type of obesity, which may prove useful regardless of individual’s ancestry and can be followed by tailored clinical intervention." (PMID 35574020, 2022). "APF lost its effects of anti-insulin resistance, obesity, and NAFLD without leptin regulation but still had minimal influence on pancreas and adipose tissues." (PMID 36046814, 2022). "The authors proposed that a lack of POMC neuron activation by leptin and insulin downregulated the sympathetic tone in brown adipose tissue (BAT) to promote obesity." (PMID 36499772, 2022). "In conclusion, in individuals with obesity, those with BED showed greater psychiatric comorbidity, worse eating patterns, worse inflammatory profile, and higher circulating leptin and GLP-1 levels than those without BED." (PMID 35758834, 2022). "Although obesity was absent, the HFD group showed increased percent weight gain, epididymal fat tissue, and leptin expression." (PMID 36387539, 2022). "On the other hand, in mice models of obesity, there was no improvement of anti-CTLA-4 treatment response until leptin was neutralized using soluble mouse leptin receptors, which lead to an increase in co-stimulatory CD86 expression." (PMID 35164764, 2022). "The relationships between corrected VFA-aBIA and obesity-related clinical factors were analyzed, including non-alcoholic fatty liver disease (NAFLD) and serum leptin and adiponectin levels." (PMID 35887911, 2022). "Reported more recently, the central blockade of the glucose-dependent insulinotropic polypeptide receptor signaling reverses obesity in DIO mice but not in Lepob/ob mice, proposing a central and potentially cell-autonomous mechanism of leptin sensitization." (PMID 35323110, 2022). "We have shown that pre-pubertal children with obesity and with NAFLD have significantly lower z-scores of circulating leptin levels than children without NAFLD." (PMID 35677722, 2022). "In addition, individuals with extremely severe obesity in young adulthood with negative results from genetic analysis of the leptin-melanocortin signalling pathway may benefit from a large-scale genetic investigation involving whole exome or whole genome sequencing." (PMID 35574020, 2022). "In conclusion, we showed that pre-pubertal children with obesity and with NAFLD had lower z-scores of circulating leptin levels than children without NAFLD." (PMID 35677722, 2022).